BHLHE40-AS1 (BHLHE40 antisense RNA 1)
Gene: Long non-coding RNA gene on chromosome 3 (4,896,806 to 4,980,414, reverse strand). Ensembl gene ENSG00000235831.
Gene Ontology:
Biological process: SRP-dependent cotranslational protein targeting to membrane, signal sequence recognition
Cellular component: signal recognition particle, endoplasmic reticulum targeting